TRPM3 (transient receptor potential cation channel subfamily M member 3)
Diseases named in the same sentence as TRPM3 in open-access papers (continued):
Sharing a sentence is not in itself a finding about the gene and the disease.
channelopathies (6 papers, 2021 to 2025). "Genetic variations in the human TRPM3 gene (TRPM3) have been associated with a broad spectrum of inherited “channelopathies” and acquired diseases or conditions." (PMID 38334649, 2024). "The disease-associated variants consistently result in a pronounced gain of channel function, providing strong support for the hypothesis that increased channel activity, potentially leading to neuronal hyperexcitability and cellular calcium overload, underlies a spectrum of TRPM3 channelopathies." (PMID 36648066, 2023). "Our current data aligns with previous research and provides evidence of impaired TRPM3 as a consistent biomarker in NK cells from long COVID patients, suggesting the involvement of channelopathy in the pathophysiology of this condition." (PMID 40458265, 2025). "Like other channelopathies, the activation of the alternative pathway of TRPM3 might produce Na+ influx at the resting membrane potential, resulting in an exacerbate TRPM3-dependent pain." (PMID 37851173, 2023). "The concentrations required to inhibit TRPM3 and its mutants are comparable to the therapeutic plasma levels of primidone, suggesting that primidone may be used as a rational therapy for this channelopathy." (PMID 33853504, 2021).
epileptic encephalopathies (6 papers, 2021 to 2025). "Analysis of gain-of-function mutations of TRPM3 revealed that TRPM3 plays a role in the development of neuronal disorders, including epileptic encephalopathies." (PMID 40305282, 2025). "Recently, rare de novo variants in TRPM3 were identified in individuals with developmental and epileptic encephalopathy, but the link between TRPM3 activity and neuronal disease remains poorly understood." (PMID 36648066, 2023). "Recent reports showed that two mutations in TRPM3 are associated with a developmental and epileptic encephalopathy, pointing to an important role of TRPM3 in the human brain." (PMID 33853504, 2021). "Furthermore, analysis of mutated TRPM3 channels revealed that TRPM3 plays an important role in the development of neuronal disorders, including epileptic encephalopathies and the development of an inherited form of early-onset cataract." (PMID 40871473, 2025). "Supporting this hypothesis, the gain-of-function mutation P1069Q, located adjacent to a CHS density, increases TRPM3 sensitivity and is associated with developmental and epileptic encephalopathies 4–6." (PMID 39896661, 2025). "The Gβγ subunit of heterotrimeric G proteins blocks TRPM3, leading to pain reduction and providing insights into the pain-relieving mechanisms of opioid analgesics.TRPM3 has VUS variants associated with developmental and epileptic encephalopathy and trigeminal neuralgia." (PMID 37893054, 2023).
autism (5 papers, 2014 to 2024). Persistent deficits in social interaction and communication and interaction as well as a markedly restricted repertoire of activity and interest as well as repetitive patterns of behavior. "Rare deletions involving coding exons in TRPM3 have been reported in Kabuki syndrome and autism, and a TRPM3 variant has been implicated in an autosomal dominant form of centrofacial pruritis." (PMID 38334649, 2024). "Rare deletions involving TRPM3 have been reported in cases of Kabuki syndrome and autism, whereas, common non-coding variants in TRPM3 have been tentatively associated with longevity and elevated levels of low-density lipoprotein cholesterol and triglycerides." (PMID 25090642, 2014). "Since ocular abnormalities were not reported in the autism family, and we do not have any evidence of autism in the family studied here, the role of TRPM3 in autism remains unclear." (PMID 25090642, 2014). "In humans, rare deletions involving TRPM3 have been reported in one case of Kabuki syndrome (KS, OMIM 147920), and in a nuclear family with two cases of autism." (PMID 25090642, 2014). "Secondly, we are aware of a case report of brothers with Becker muscular dystrophy, autism, and a partial (nine-exon) TRPM3 deletion; however, the deletion did not cosegregate with disease." (PMID 31278393, 2019).
clear cell renal cell carcinoma (5 papers, 2017 to 2024). "Similarly, TRPM3 has been found upregulated in clear cell renal cell carcinoma cell lines 786-O or A498 and its knockdown or inhibition suppressed growth of tumours generated from renal carcinoma cells in orthotopic xenograft mouse models, suggesting an oncogenic role for TRPM3 in renal cancer." (PMID 32575381, 2020). "A previous study demonstrated that TRPM3, another TRP channel, increases Ca2+ influx and promotes clear cell renal cell carcinoma growth by stimulating autophagy." (PMID 39334351, 2024). "miR-204 indirectly inhibits TRPM3-mediated downstream LC3B-related autophagy through Cav-1, thereby inhibiting the progression of clear cell renal cell carcinoma." (PMID 34955837, 2021).
insulinoma (5 papers, 2016 to 2025). "Stimulation of TRPM3 channels in insulinoma cells leads to the upregulation of c-Fos promoter activity and an increase in c-Fos biosynthesis." (PMID 40305282, 2025). "CREB is phosphorylated in TRPM3-expressing insulinoma cells that have been stimulated with pregnenolone sulfate." (PMID 40305282, 2025). "Stimulation of TRPM3 in insulinoma cells results in the phosphorylation of c-Jun, indicating that c-Jun is activated following TRPM3 stimulation." (PMID 40305282, 2025). "Experiments with INS-1 insulinoma cells showed that TRPM3-mediated signaling is prevented by the presence of inhibitors of L-type voltage-gated Ca2+ channels." (PMID 40305282, 2025). "TRPM3 also upregulates c-Jun and c-Fos promoter activity and stimulates CRE-controlled reporter gene transcription in insulinoma and pancreatic β-cells, in a TRPM3-dependent manner." (PMID 33603674, 2021). "Stimulation of endogenously expressed TRPM3 channels has been shown to trigger insulin secretion by insulinoma cells." (PMID 33603674, 2021). "This is supported by recent studies, which demonstrated expression of TRPM3 in rat pancreatic INS-1 insulinoma cells and in mouse pancreatic islets." (PMID 27548188, 2016). "TRPM2, in addition to TRPM3, TRPM4, and TRPM5, was described in rodent insulinoma cell lines and in mouse islets." (PMID 27548188, 2016).
migraine (5 papers, 2022 to 2025). "Taken together, our study suggests that activation of TRPM3 channels may be involved in triggering pain generation in meninges and seems to play a prominent role in mechanisms underlying sex differences in migraine pathology." (PMID 35012445, 2022). "Considering the broad hormonal regulation profile of TRPM3 channels and observing the significant difference in TRPM3 channel activity between males and females, we propose that TRPM3 channels play an important role in the mechanisms underlying sex differences in migraine." (PMID 35012445, 2022). "Based on our own RNA-sequencing data, genes previously known to link with migraine through genome-wide analysis or various migraine models, Crebbp, Trpm3, Zmynd8 and Akt1 are among the potential candidate genes that have especially caught our interest." (PMID 39390364, 2024). "We found expression induction of several migraine-related genes (Crebbp, Trpm3, Atp5α1 and Akt1) were downregulated by photophobia, notably this reduction was restored by SRCT in our study." (PMID 39390364, 2024). "This study, for the first time, demonstrates the presence of TRPM3 channels in the peripheral part of meningeal TG nerves that are considered relevant for migraine pathogenesis." (PMID 35012445, 2022). "Here we show that TRPM3 channels are present in the meningeal part of the trigeminovascular system and can play a particular role in the generation of migraine pain in females." (PMID 35012445, 2022). "The intriguing role of female hormones in modulating the activity of TRPM3 channels deserves further exploration in in vivo models of migraine." (PMID 35012445, 2022). "Considering the rising spiking activity in meningeal afferents as a nociceptive effect, we here provide first evidence of TRPM3 channels in relation to the site of origin of migraine pain." (PMID 35012445, 2022). "Here we propose that mechanosensitive ‘transient receptor potential melastatin 3’ (TRPM3) channels, which were recently shown to be expressed in human sensory neurons, are involved in the generation of migraine pain." (PMID 35012445, 2022). "Together, we revealed a specific mechanosensitive profile of nociceptive firing in females and suggest TRPM3 channels as a potential novel candidate for the generation of migraine pain, with particular relevance to females." (PMID 35012445, 2022). "Together, these neuronal and vascular TRPM3-related mechanisms may help explaining the higher prevalence and severity of migraine attacks in females." (PMID 41031400, 2025). "Given the role of transient receptor potential melastatin 3 (TRPM3) channels in mechanical activation, as well as hormonal regulation, these channels may play a role in the sex difference in migraine." (PMID 35012445, 2022). "Hence, we provided first experimental evidence of the presence and function of TRPM3 channels in nerves that are considered very relevant for migraine pathogenesis." (PMID 35012445, 2022). "Therefore, taking into account the molecular and mechanosensitive properties of TRPM3 channels, we envisage TRPM3 channels as an attractive new target for drug interventions in migraine." (PMID 35012445, 2022). "Therefore, one can speculate that regulation of TRPM3 channels by sex hormones might, in fact, represent an endogenous inhibitory mechanism that modulates migraine attacks in females." (PMID 35012445, 2022). "Other TRP channels, such as TRPV4, TRPM3, TRPC4 and TRPM8, remain reliable candidates to be involved in migraine pain signaling with potential to be drug targets." (PMID 38221631, 2024). "Although TRPM3 channels have been intensively studied in somatosensory neurons of DRGs and TG ganglia, they have not been considered as relevant to migraine pathophysiology and had not been identified in the meningeal afferents." (PMID 35012445, 2022).
migraine (continued). "In addition, we assessed the relative contribution of mechanosensitive TRPM3 channels and that of mechanosensitive Piezo1 channels and transient receptor potential vanilloid 1 (TRPV1) channels to nociceptive firing relevant to migraine in both sexes." (PMID 35012445, 2022). "Therefore, TRPM3 channels have been proposed as a clinically promising pharmacological target for analgesic strategies, although this has not been considered yet for migraine." (PMID 35012445, 2022).
renal cell carcinoma (5 papers, 2015 to 2023). "Currently, only a few channels of the TRP family have been characterized as having a role in tumor angiogenesis, such as TRPV4, TRPV3, TRPM3, and TRPA1, demonstrated in lung carcinoma, renal cell carcinoma, cancer-associated fibroblast, and prostate cancers." (PMID 37576552, 2023). "miR-204-5p was demonstrated to regulate expression of TRPM3 both directly and indirectly in renal cell carcinoma cell lines, as part of a network involved in regulation of autophagy." (PMID 26714269, 2015). "Therefore, an interplay between VHL and TRPM3 involving two miRNAs, namely miR-204 and miR-214, controls autophagy activation and renal cell carcinoma growth." (PMID 28459042, 2017).
COVID-19 (4 papers, 2022 to 2024). A disease caused by infection with severe acute respiratory syndrome coronavirus 2. "Further investigation into TRPM3 function may elucidate the pathomechanism, provide a diagnostic and therapeutic target for post COVID-19 condition patients and commonalities with ME/CFS patients." (PMID 35986236, 2022). "Our recent study suggested that NK cells from post-COVID-19 condition patients also had TRPM3 ion channel dysfunction similar to ME/CFS patients." (PMID 38765011, 2024). "After 24-h treatment with 200 μM NTX, whole-cell patch-clamp experiments were performed to assess TRPM3 activity in NK cells from post-COVID-19 condition and HC participants." (PMID 38765011, 2024). "In conclusion, TRPM3 dysfunction in post-COVID-19 condition and ME/CFS participants suggests impairment in ion mobilization and consequently results in Ca2+ signaling and cell homeostasis disturbance in both diseases." (PMID 38765011, 2024). "Whole-cell patch-clamp was performed to characterize TRPM3 ion channel activity in freshly isolated NK cells of post COVID-19 condition (N = 9; 40.56 ± 11.26 years), ME/CFS (N = 9; 39.33 ± 9.80 years) and healthy controls (HC) (N = 9; 45.22 ± 9.67 years)." (PMID 38765011, 2024). "This investigation proposes NTX as a potential therapeutic intervention and TRPM3 as a treatment biomarker for post COVID-19 condition." (PMID 38765011, 2024). "This study also reports, for the first time, TRPM3 ion channel activity was restored in NK cells isolated from post COVID-19 condition patients after in vitro treatment with NTX." (PMID 38765011, 2024). "As we recently reported, PregS induced TRPM3 currents were significantly reduced in NK cells from the post-COVID-19 condition group compared with those from HC (p < 0.0001), and were not significantly reduced from the ME/CFS group (p = 0.8578)." (PMID 38765011, 2024). "Our results suggest that TRPM3 function in NK cells from post-COVID-19 condition participants was restored after in vitro treatment with 200 μM NTX." (PMID 38765011, 2024). "In this investigation, we aimed to validate our previous study of impaired TRPM3 channel in NK cells from post-COVID-19 condition and ME/CFS participants." (PMID 38765011, 2024). "This study showed that TRPM3 ion channel activity was restored in NK cells from post-COVID-19 condition patients after in vitro treatment with 200 μM NTX for 24 h." (PMID 38765011, 2024). "The NTX treatment restored TRPM3 ion channel activity in the post-COVID-19 condition group, facilitating Ca2+ influx for intracellular signaling pathways." (PMID 38765011, 2024). "Our previous research has suggested that people suffering from post-COVID-19 condition also have TRPM3 dysfunction in NK cells, which is a biomarker consistently identified in ME/CFS patients." (PMID 38765011, 2024). "Given that TRP ion channels are vulnerable to threats/stressors, such as viruses, further research is required to differentiate TRPM3 dysfunction in ME/CFS patients compared with post COVID-19 condition." (PMID 35986236, 2022). "PregS-induced TRPM3 amplitude was significantly reduced in post COVID-19 condition compared with HC (p = 0.0039)." (PMID 35986236, 2022). "For the first time, we report a significant reduction in amplitude of TRPM3 ion channel current after PregS stimulation in isolated NK cells from post COVID-19 condition patients compared with HC." (PMID 35986236, 2022). "The present study provides significant and novel finding of impaired TRPM3 ion channel activity in post COVID-19 condition." (PMID 35986236, 2022). "The aim of this investigation was to determine the activity of TRPM3 ion channels using whole-cell patch-clamp measurements in isolated NK cells from post COVID-19 condition, ME/CFS and healthy control (HC) after modulation with PregS and ononetin." (PMID 35986236, 2022). "Importantly, PregS-induced TRPM3 currents were significantly restored in NTX-treated NK cells from post COVID-19 condition compared with HC." (PMID 38765011, 2024).
COVID-19 (continued). "In addition, we also intended to further investigate the potential effects of in vitro treatment with NTX on TRPM3 dysfunction in NK cells from post-COVID-19 condition patients." (PMID 38765011, 2024). "Indeed, a significant reduction in TRPM3 amplitude after PregS (100 μM) application was shown in freshly isolated NK cells from post-COVID-19 condition participants compared with cells from the HC group (p < 0.0001)." (PMID 38765011, 2024). "In addition, NK cells from ME/CFS and post-COVID-19 condition groups were resistant to ononetin, a TRPM3 inhibitor, in the presence of PregS." (PMID 38765011, 2024). "However, after the same incubation processes of NK cells from the post-COVID-19 condition group, TRPM3 currents were significantly increased in the NTX-treated group (p < 0.0001)." (PMID 38765011, 2024). "Impaired TRPM3 channel activity in post COVID-19 condition patients suggest impaired ion mobilisation which may consequently impede cell function resulting in chronic post-infectious symptoms." (PMID 35986236, 2022). "We report, for the first time, TRPM3 ion channel dysfunction in post COVID-19 condition." (PMID 35986236, 2022). "The results of this investigation suggest that post COVID-19 condition patients may have impaired TRPM3 ion channel function and provide further evidence regarding the similarities between post COVID-19 condition and ME/CFS." (PMID 35986236, 2022). "Importantly, future investigations may examine the TRPM3 ion channels as a potential target for treatment of post COVID-19 condition." (PMID 35986236, 2022). "Therefore, impaired TRPM3 ion channels may contribute to post COVID-19 condition through consequences of impaired Ca2+ signalling, thus impeding Ca2+-dependent cellular pathways resulting in impaired NK cell cytotoxicity." (PMID 35986236, 2022). "This research aimed to: i) validate impaired TRPM3 ion channel function in post COVID-19 condition patients compared with ME/CFS; and ii) investigate NTX effects on TRPM3 ion channel activity in post COVID-19 condition patients." (PMID 38765011, 2024). "Whole-cell patch-clamp technique was used to measure TRPM3 ion channel activity in isolated NK cells of N = 5 ME/CFS patients, N = 5 post COVID-19 patients, and N = 5 healthy controls (HC)." (PMID 35986236, 2022). "TRPM3 function in non-treated NK cells from post-COVID-19 condition and HC groups was assessed in the whole-cell mode after 24 h of incubation without NTX as a control." (PMID 38765011, 2024). "Importantly, NTX restored TRPM3 in NK cells from both post-COVID-19 condition and ME/CFS groups, suggesting TRPM3 dysfunction overlap in the pathomechanism of both conditions." (PMID 38765011, 2024). "Due to the overlap observed for PregS-induced currents, TRPM3 ion channel dysfunction may provide a target for research into the pathomechanism and treatment of not only ME/CFS, but also post COVID-19 condition." (PMID 35986236, 2022). "In fact, TRPM3 activity by pregnenolone sulfate (PregS), a TRPM3 agonist, in NK cells from post-COVID-19 condition patients mimicked the results from ME/CFS patients, while a significant difference was found between post-COVID-19 condition patients and healthy controls (HC)." (PMID 38765011, 2024). "Therefore, TRPM3 ion channel dysfunction in NK cells may play a pivotal role in the pathomechanism of ME/CFS and also in post COVID-19 condition." (PMID 35986236, 2022). "Additionally, NTX-treated NK cells from post-COVID-19 condition patients in part became sensitive to ononetin when compared with non-treated cells (p < 0.0001), confirming that TRPM3 ion channel currents were evoked by PregS stimulation in NTX-treated NK cells from post-COVID-19." (PMID 38765011, 2024). "Therefore, future research might assess in vitro effects of NTX treatment in the restoration of physiological TRPM3 in NK cells and also the potential pharmacological benefit of LDN in post COVID-19 condition patients, as previously indicated in ME/CFS patients." (PMID 35986236, 2022).